NAMPTP1 (nicotinamide phosphoribosyltransferase pseudogene 1)
Synonyms: bA92J19.4; NAMPTL; PBEF2
Gene: Processed pseudogene on chromosome 10 (36,521,721 to 36,524,234, reverse strand). Ensembl gene ENSG00000229644.
Diseases named in the same sentence as NAMPTP1 in open-access papers:
NAMPTP1 is named in the same sentence as 2 diseases in open-access papers, as found by Europe PMC text mining. Sharing a sentence is not in itself a finding about the gene and the disease. The quoted sentences say what the papers report.
pancreatic cancer (2 papers, 2020 to 2021). "Based on the results from expression and correlation analysis, NAMPTP1/HCG11-hsa-miR-26b-5p-COL12A1 competing endogenous RNA (ceRNA) sub-network was associated with the prognosis of pancreatic cancer." (PMID 33027767, 2020). "Based on integrated bioinformatics analysis, a new potential COL12A-miR-26b-5p-HCG11/NAMPTP1 regulatory axis was successfully constructed in pancreatic cancer." (PMID 33027767, 2020). "Only 3 pseudogenes (NAMPTP1 NCF1B NCF1C) were remarkably upregulated in pancreatic cancer samples compared to normal controls." (PMID 33027767, 2020). "Based on the ceRNA hypothesis, a novel HCG11/NAMPTP1-miR-26b-5p-COL12A1 triple sub-network was constructed, which showed that overexpressed lncRNAs/pseudogenes mediate downregulation of hsa-miR-26b-5p leading to increased expression of COL12A1 in the progression of pancreatic cancer." (PMID 33027767, 2020). "Expression correlation analysis further demonstrated that NAMPTP1 has a negative correlation with miR-26b-5p, indicating that it may play vital roles in regulating hsa-miR-26b-5p-COL12A axis in the progression of pancreatic carcinoma." (PMID 33027767, 2020).
cancer (1 paper, 2020). A tumor composed of atypical neoplastic, often pleomorphic cells that invade other tissues. "Using GEPIA database, three (NAMPTP1 NCF1B NCF1C) out of 92 predicted pseudogenes were found to be remarkably upregulated in cancer samples." (PMID 33027767, 2020).